TNF (tumor necrosis factor)
Diseases named in the same sentence as TNF in open-access papers (continued):
Sharing a sentence is not in itself a finding about the gene and the disease.
cerebrovascular disease (25 papers, 2013 to 2026). "Prothrombotic or proinflammatory candidate genes for CP such as TGF-Beta-1, MMP-2, MTFHR-C677T, and TNF-alpha 308, have all been associated with increased cerebrovascular disease risk or worse cerebrovascular disease prognosis." (PMID 24223882, 2013). "Furthermore, previous studies have found associations between the genetic polymorphisms of TNF-α and cerebrovascular disease susceptibility." (PMID 35781632, 2022). "Tumor necrosis factor (TNF) and soluble intercellular adhesion molecule 1 (sICAM-1) reflect inflammation levels in the body, and their increased expression is often associated with acute cerebrovascular disease events." (PMID 26016434, 2015). "TNF-α level is increased in the body suffering from malignant tumors, cardiovascular and cerebrovascular diseases, chronic inflammatory diseases, and fractures." (PMID 31852483, 2019). "Additionally, elevated levels of pro-inflammatory cytokines, including tumor necrosis factor α (TNF-α) and interleukin 6 (IL-6), in these patients are linked to vascular damage and an increased risk of cardiovascular and cerebrovascular diseases." (PMID 39596351, 2024). "CRP, one of the acute response phase proteins, can reflect the level of inflammation in the body and the progress of cerebrovascular disease; TNF-α and IL-6 are proinflammatory factors, both of which can promote the chemotaxis and adhesion of inflammatory factors, and adversely affect patients." (PMID 35692885, 2022). "Besides, the age > 65 years, the aortic plaque, carotid artery stenosis, cerebrovascular diseases, HDL-C, fasting plasma glucose, hs-CRP, TNF-α, white blood cell and surgery duration were also associated with the POCD risk." (PMID 32271371, 2020). "In addition to these results, the current study reveals a significant association of serum and urinary mtDNA levels with pro-inflammatory biomarkers TNFα and ICAM-1, which intervene in the pathogenesis of both DKD and cerebrovascular disease." (PMID 38672515, 2024). "Plasma levels of LDL-C, TNF-α, and PTX3 were increased significantly in the CAS group patients vs. the CAS-free group (p = 0.002, 0.002, 0.000, respectively), and family history of cerebrovascular disease was significantly more common in the CAS group (p = 0.005)." (PMID 31998222, 2019). "Within the CAS group, LDL-C, TNF-α, and PTX3 were significantly elevated in the SS group (p = 0.049, 0.002, 0.001, respectively) compared to the MS group, however no statistical difference infamily history of cerebrovascular disease was noted between these two groups (p = 1.000)." (PMID 31998222, 2019).
essential hypertension (25 papers, 2007 to 2025). Hypertension that presents without an identifiable cause. "The observed increase in TNF-α expression promotes activation of the death receptor-mediated pathway resulting from the significant upregulation of cardiac caspases 8 and 9 in the heart of rats with primary hypertension." (PMID 30223427, 2018). "Clinical data demonstrated that inflammatory biomarkers such as CRP, IL-6, and TNF-α significantly increased in primary hypertension, and this increase is observed significantly more often in nondippers and is associated with the onset of target organ damage and cardiovascular events." (PMID 28757677, 2017).
monocytic leukemia (25 papers, 2011 to 2025). "In so doing, we treated the THP-1 human monocytic leukemia cell line with ΔFN3 proteins alone or in combination with TNF-α for 3 h, followed by RT-PCR." (PMID 41226598, 2025). "Human monocyte leukemia U937 cells readily undergo apoptosis when they are treated with TNF-α, anti-Fas antibody and anticancer drugs such as cisplatin and doxorubicin." (PMID 38827790, 2024). "The diatom Cylindrotheca closterium showed anti-inflammatory properties inhibiting TNFα release in human monocytic leukemia cells." (PMID 32139778, 2020). "The PPAR-γ agonist inhibited TF expression in response to TNF-α in human umbilical vein endothelial cells, human monocytic leukemia cell line, and human umbilical arterial smooth muscle cells." (PMID 22140576, 2011). "The amount of IL-1β and TNF-α mRNA expressed in a human monocytic leukemia cell line (THP-1) is visualized and counted using single-molecule fluorescent in-situ hybridization (smFISH) following exposure of the cells to lipopolysaccharide (LPS), an outer-membrane component of Gram-negative bacteria." (PMID 34211022, 2021). "None of the strains could invade macrophages, although incubation of the C. showae strains with the THP-1 human monocytic leukemia cell line for 6 h led to proinflammatory cytokine production (TNF-α, IL-1b and IL-8)." (PMID 31169073, 2019). "In particular, menadione inhibited nuclear factor kappa-light-chain-enhancer of activated B cell (NF-κB) activation and thereby reduced expression of the proinflammatory cytokines such as IL-1β, IL-6, IL-8, and TNF-α in AGS as well as in THP-1 (monocytic leukemia cell) cell lines." (PMID 30866458, 2019). "Similarly, other S100A8 and S100A9 regulators, such as IL-6 and TNFα, have been identified on human monocytic leukemia cells." (PMID 24956170, 2014). "For instance, silver carp bone hydrolysate lowered the levels of tumor necrosis factor-alpha (TNF-α) and interleukin-1 beta (IL-1β), two key mediators of the inflammatory response in LPS-treated human monocytic leukemia cells." (PMID 41009001, 2025). "DHA inhibits the inflammatory cytokines, such as IL-6, and TNF-α and IL-1β expression induced by LPS in THP-1 cells, which is the human monocytic leukemia cell line." (PMID 36741381, 2022). "The human monocytic leukemia cell line THP-1 exhibited only a low spontaneous migration through an endothelial monolayer of control cells, which dramatically increased in TNF + HG treated endothelial cells." (PMID 31346222, 2019). "We herein report the effect of 19 plant extracts on TNF-α and CCL2 release by lipopolysaccharide- (LPS-) stimulated THP-1 cells, a human monocytic leukemia cell line, along with their radical scavenging activity on DPPH." (PMID 25878716, 2015). "Meanwhile, L971 could also inhibit IκB degradation induced by TNFα and IKK phosphorylation induced by LPS in human monocytic leukaemia THP‐1 cells, indicating its inhibitory activity for NFκB signalling." (PMID 34018320, 2021). "It was previously reported that ZVAD inhibited apoptosis but induced necroptosis, whereas Z-Asp-CH2-DCB (ZAsp)—a caspase inhibitor preferential to caspase-3—suppressed apoptosis without inducing necroptosis in TNF-treated U937 human monocytic leukemia cells." (PMID 27739412, 2016). "On the other hand, magnetic nanoparticles induced formation of membranous ferroportin and incited secretion of ferritin, TNF-α, and IL-10 in human histiocytic lymphoma cells (U937) and human monocyte leukemia cells without any decrease of cell viability." (PMID 27106358, 2016).
nasal polyps (25 papers, 2008 to 2026). "An association of TNF rs1800629 with nasal polyposis has also been found." (PMID 35456412, 2022). "Indeed, another recent study has indicated that the -308G polymorphism in the TNF-α gene may also be associated with nasal polyposis." (PMID 23472126, 2013). "TNFα recruits and accumulates eosinophils via the upregulation in the nasal polyps of the chemokine eotaxin and the adhesion molecules VCAM-1 and VCAM-2 on the fibroblasts." (PMID 36986875, 2023). "TNF-α is frequently regarded as a key pro-inflammatory factor in the pathogenesis of CRS due to the fact that nasal polyp tissues have been observed to express markedly high levels of TNF-α." (PMID 37771597, 2023). "TNFα mRNAs and protein levels were found to be higher in the nasal polyps than in the inferior turbinate tissues." (PMID 36986875, 2023). "In the present study, we investigated Raftlin expression in nasal polyp tissues (with controls and CRSwNP smoker samples) in the Taiwanese population and assessed its relationship with cytokines IL-17 and TNF-α." (PMID 36139155, 2022). "In a subsequent review, a Hungarian group showed that the TNF rs1800629 A allele was a genetic predisposition factor in a subgroup of patients with aspirin sensitivity, chronic rhinosinusitis (CRS), and nasal polyposis (NP)." (PMID 35456412, 2022). "This study investigates the expression of Raftlin in cigarette smokers and in chronic rhinosinusitis with nasal polyps (CRSwNP), as well as evaluating its correlation with interleukin-17 (IL-17) and tumor necrosis factor-α (TNF-α) levels." (PMID 36139155, 2022). "TNF-α stimulates adhesion molecule expression in endothelial cells and upregulates CC chemokine ligand 2 in fibroblast cultures derived from nasal polyps, thereby facilitating the recruitment of inflammatory cells." (PMID 30040868, 2018). "TNF-alpha significantly induced pro-inflammatory mediators production, both at mRNA and protein levels, in nasal polyps fibroblasts cultures." (PMID 22030969, 2011). "SEB induced a significantly higher release of TNF-α and IL-2 in nasal polyps from AERD patients after 4 hours of stimulation." (PMID 23282714, 2010). "We next examined the synergistic effects of several IL-17 family members and TNF-α on nasal polyp fibroblasts." (PMID 23283206, 2009). "Combined stimulation with IL-17A and TNF-α induced further upregulation of MIP-3α/CCL20 expression in the nasal polyp fibroblasts." (PMID 23283206, 2009). "The objective of this study was to demonstrate the expression of MIP-3α/CCL20 in nasal polyp fibroblasts after stimulation with proinflammatory cytokines such as interleukin-17 (IL-17) and tumor necrosis factor-α (TNF-α)." (PMID 23283206, 2009). "IL-17A and TNF-α synergistically induced MIP-3α/CCL20 production by nasal polyp fibroblasts in a dose- and time-dependent manner." (PMID 23283206, 2009). "In HNECs derived from human nasal polyps levofloxacin was found to down-regulate the synthesis of pro-inflammatory cytokines TNF-α, IFN-γ and IL-8." (PMID 18664275, 2008). "Besides, our data indicated that the levels of IL-17 and TNF-α significantly correlated with Raftlin levels from whole nasal polyp tissues and in columnar cells." (PMID 36139155, 2022). "In Asian patients with CRS, the expression of IL-22 is associated with IL-17A and TNFα and the absence of nasal polyps." (PMID 35455762, 2022). "Moreover, TNF-α mRNA and protein expression levels are increased in nasal polyps versus inferior turbinate tissues." (PMID 30040868, 2018). "Overproduction of IL-8 and TNF-α attracts more inflammatory cells into nasal polyp tissues." (PMID 30040868, 2018). "Chronic rhinosinusitis without nasal polyps with TNFα >20 pg/ml was associated with the mucosal presence of Pseudomonas aeruginosa." (PMID 26275068, 2015).
nasal polyps (continued). "Spontaneous release of IL-5, and TNF-α could be observed in nasal polyp tissue, which was significantly inhibited by the combination of S. baicalensis and E. senticosus, but no single component, at a concentration of 2 μg/mL of each component (data not shown)." (PMID 22272213, 2012). "However, in the present study, we have demonstrated that IL-17A and TNF-α synergistically induced MIP-3α/CCL20 in nasal polyp fibroblasts." (PMID 23283206, 2009). "It is interesting to speculate whether IL-17A, which is released from Th17 cells, is capable of inducing MIP-3α/CCL20 production in nasal polyp fibroblasts synergistically with TNF-α, which is abundant in nasal polyps." (PMID 23283206, 2009). "Moreover, high levels of IL-8 and TNF-α might account for the increased number of total inflammatory cells or neutrophils accumulating in the nasal polyps of smoking CRSwNP patients." (PMID 30040868, 2018). "CS exposure enhanced PGE2 production and the proinflammatory cytokines IL-8 and TNF-α and downregulated the expression levels of EP2 and EP4 receptors in nasal polyps of CRS patients." (PMID 30040868, 2018). "SEB resulted in a significant release of IL-1, TNF-α, IFN-γ, Il-2, IL-5 and IL-17 from nasal polyp tissue, indicating the stimulation of all prominent T helper cell populations." (PMID 22272213, 2012). "Similarly, nasal polyp tissue displays a SEB-stimulated significant release of IL-1, TNFα, IFN-γ, IL-2, IL-5 and IL-17." (PMID 25875480, 2015). "Although a recent study showed that hypoxia might induce Cyr61 and IL-8 secretion in nasal polyp fibroblasts, no direct evidence demonstrated that Cyr61 induces IL-8 production under an inflammatory environment via an IL-1β/TNF-α independent pathway." (PMID 24517278, 2013). "However, increased TNF-α expression was observed in both atopic and nonatopic nasal polyps." (PMID 23283206, 2009). "After 18 hours, SEB significantly induced the release of TNF-α, IFN-γ, IL-2, and IL-5 in both nasal polyp-asthma groups compared with healthy controls but without statistical differences between disease groups." (PMID 23282714, 2010). "Combined stimulation with TNF-α plus IL-17A or IL-17F, but not IL-17E, synergistically induced release of MIP-3α/CCL20 by the nasal polyp fibroblasts." (PMID 23283206, 2009).
non-melanoma skin carcinoma (25 papers, 2013 to 2025). "Associations have been shown between thiopurines and non-melanoma skin cancers (NMSCs) and between the anti-tumor necrosis factor (TNF) and melanoma skin cancers (MSCs)." (PMID 39274426, 2024). "Patients that were treated with anti-TNF drugs demonstrated an increased risk for non-melanoma skin cancers (NMSC)." (PMID 36980651, 2023). "Although there is a debate on the association between anti-TNF and malignancies, there is increasing evidence that links risk of non-melanoma skin cancer with anti-TNF therapy." (PMID 36104053, 2022). "However, there has been an inconsistent and controversial correlation between anti-TNF-α therapies and increased risk for non-melanoma skin cancer in humans." (PMID 29228682, 2017). "Chronic immunosuppression can lead to malignancy due to decreased immune surveillance, but TNF-α inhibitors have been found to be largely safe aside from the development of non-melanoma skin cancer." (PMID 39941759, 2025). "Reported cutaneous side effects from TNF-α blockers include injection site reactions, infusion reaction skin manifestations, infections, non-melanoma skin cancer, and psoriasis." (PMID 39064094, 2024). "While combination of acitretin and PUVA is beneficial, combining TNF-α inhibitors and phototherapy too produces better and faster results but long term risks of Non Melanoma Skin Cancers (NMSCs) may preclude their use together." (PMID 34490293, 2021). "Meta-analysis of registries and long-term extension studies showed no increased risk for total malignancies as well as for non-melanoma skin cancer when comparing TNF-inhibitors and the classical disease modifying anti-rheumatic drugs (DMARDs) treatment." (PMID 24642038, 2014). "In randomized controlled trials (RCT) TNF-inhibitors did not increase the risk of solid malignancies, except for non-melanoma skin cancer (risk doubled compared to control treatment)." (PMID 24642038, 2014).
Pruritus (25 papers, 2010 to 2025). Pruritus is an itch or a sensation that makes a person want to scratch. "Our experiments argue for a determining role of TNF-α and IL-6 in DM-associated pruritus, and further experiments are required to study the role of PPAR-γ." (PMID 37250649, 2023). "Pruritus-caused skin scratches can severely damage the skin epidermal barrier, and subsequently, immunomodulatory proteins such as tumor necrosis factor (TNF)-α, interferon (IFN)-γ, and interleukin (IL-4) accumulate in the skin epithelial cells." (PMID 36164402, 2022). "Our results argue that cutaneous disease activity, TNF-α, and IL-6 might play a central role in DM-associated itch, while TRPV4 plays a central role in tissue regeneration." (PMID 37250649, 2023). "In addition, studies using itch-deficient (Itch−/−) mice showed enhancement of phosphorylation of p38α in skin lesions, and the levels of proinflammatory cytokines such as TNF-α and IL-1β were increased in the skin of Itch−/− mice." (PMID 35798870, 2022). "The pruritus is potentially mediated by cytokines, including IL-6 and TNF-α, which are upregulated during immune activation." (PMID 40271531, 2025). "Vitamin D has been shown to suppress the production of pro-inflammatory cytokines such as IL-6, TNF-α, and IL-17 while promoting regulatory T-cell activity, thereby reducing skin inflammation and pruritus intensity." (PMID 40332575, 2025). "Vitamin D has been shown to downregulate the production of pro-inflammatory cytokines, such as TNF-α, IL-6, and hs-CRP, which are often elevated in conditions associated with chronic pruritus." (PMID 39337471, 2024). "Clearly, some genes such as AKT1, ALB, BCL2, STAT3, JUN, ESR1, and TNF hold important positions within the network, indicating their strong relevance to the pathogenesis of pruritus and their potential as key targets for drug intervention." (PMID 39606625, 2024). "It was shown that the expression of genes encoding inflammatory mediators such as CCL4, CCL7, CCL8, CCL20, interleukin-19 (IL-19), IL-20, IL-26, IL-36A, IL-36G, and TNF-α) was unique to psoriatic skin with pruritus." (PMID 37834183, 2023). "A previous study using L. plantarum PMO 08 reported an improvement in pruritus by regulating of pro-inflammatory cytokines such as IL-4 and TNF-a." (PMID 33143293, 2020). "Thalidomide acts as an immunomodulatory drug, a tumor necrosis factor-alpha inhibitor, and a central and peripheral nerve depressant; it is effective in the treatment of various types of pruritus." (PMID 30766878, 2019). "Topical application of Danggui (Angelica sinensis) has been reported to attenuate inflammation and severity of pruritus symptoms by reducing the number of mast cells, serum IgE concentrations, and by reducing the concentration of inflammatory cytokines, such as IL-6, TNF-α, and IFN-γ." (PMID 36297351, 2022). "The induction of pruritus is due to the SP-induced production of pro-inflammatory cytokines and release of pruritogenic mediators from mast cells such as histamine, tumor necrosis factor (TNF)-α, prostaglandin D2, and leukotriene B4 via binding of SP to NKR1 on keratinocytes and mast cells." (PMID 20532044, 2010). "Hence, results of the present study indicate that the studied cytokines- IL-13, IL-31 and TNF-α, have key role in the pathogenesis of canine AD and expression of IL-13 and TNF-α genes in atopic dogs might be down-regulated with increased severity of pruritus." (PMID 34075152, 2021). "TNF-α also sensitizes nociceptive nerve endings via TNF-α receptors and increases their responsiveness, resulting in intense pruritus." (PMID 39063153, 2024). "Simultaneously, CGRP stimulates keratinocyte proliferation but also prompts the release of CGRP, interleukin-1β (IL-1β), IL-6, and tumor necrosis factor-alpha (TNF-α), leading to conditions such as rash and pruritus." (PMID 39144633, 2024).
Pruritus (continued). "Although TNF-α and IL-6 are not considered the primary cytokines in classic pruritus pathways, they are part of the broader inflammatory network involved in various pruritic conditions." (PMID 40332575, 2025). "Injection site pruritus (ROR = 19.81, 95% CI [17.61–22.28], n = 569) also displayed a pronounced signal, particularly for etanercept (ROR = 41.58, 95% CI [36.74–47.04], n = 394), which surpassed other TNF-α inhibitors in signal magnitude." (PMID 41329755, 2025). "We also identified a moderate positive correlation between TNF-alpha and the pruritus score, but not the wheal score on the blood sampling day." (PMID 40290408, 2025).